FGF23 (fibroblast growth factor 23)
Diseases named in the same sentence as FGF23 in open-access papers (continued):
Sharing a sentence is not in itself a finding about the gene and the disease.
acute kidney injury (continued). "This dissociation makes the principle that chronic phosphate burden in CKD resulting in increased serum PTH and FGF-23 levels and leading to renal osteodystrophy may not be consistent when present in PTX animals accompanied by renal failure." (PMID 26186634, 2015).
hypophosphatemic rickets (110 papers, 2010 to 2026). Rickets due to low serum phosphate concentrations, the cause of which can be nutritional or genetic. "The use of monoclonal antibodies to fibroblast growth factor 23 (FGF23) was described as a therapy for hypophosphatemic rickets in a patient with a postzygotic c.182A > G mutation in the HRAS gene." (PMID 41438146, 2025). "We examined TM5614, a PAI‐1 antagonist, as a potential therapeutic agent for FGF23‐associated hypophosphatemic rickets." (PMID 38050660, 2024). "Other causes of phosphopenic rickets, non FGF23-associated, include renal tubular disorders, hereditary hypophosphatemic rickets with hypercalciuria, and nutritional phosphate deficiency." (PMID 36817604, 2023). "Hypophosphatemic rickets is a spectrum of genetic disorder characterized by defective bone mineralization secondary to hypophosphatemia associated with excessive circulating FGF23." (PMID 36292765, 2022). "Enhanced FGF23-mediated renal phosphate loss reduces bone mineralization, resulting in hypophosphatemic rickets." (PMID 35966073, 2022). "Phosphopenic rickets, also called hypophosphatemic rickets, can either be due to dietary phosphate deficiency or impaired bioavailability, FGF23-mediated renal phosphate wasting or to primary or acquired renal tubular phosphate wasting." (PMID 34910242, 2022). "Fibroblast-growth factor 23 (FGF23)-associated hypophosphatemic rickets was historically treated with frequent doses of oral phosphate salts in combination with active vitamin D—so-called conventional treatment." (PMID 35352187, 2022). "Hypophosphatemic rickets (HR) is a rare renal phosphate-wasting disorder caused by several genetic mutations in factors leading to increase in fibroblast growth factor 23 (FGF23) signalling or secretion, and in renal phosphate transporters." (PMID 31514490, 2020). "Primary causes of excess FGF23, such as in hereditary hypophosphatemic rickets, have been associated with cardiovascular calcification in cases of excessive phosphate treatment." (PMID 29766437, 2018). "Hypophosphatemic rickets is caused by a group of genetic disorders characterized by reduced renal phosphate transport, bone malformation, and elevated fibroblast growth factor 23 (FGF23)." (PMID 27242547, 2016). "The aim of this study was to investigate the etiology of patients with hypophosphatemic rickets who exhibited serum FGF23 elevation and harbored a novel PHEX mutation." (PMID 25861491, 2015). "Regardless, our findings in Enpp1−/− mice are consistent with human genetic studies that have recently shown that Enpp1, if mutated, causes hypophosphatemic rickets resulting from increased FGF-23 levels." (PMID 22359666, 2012). "Elevated levels of FGF-23, an inhibitor of renal Pi re-absorption, have been observed in patients suffering from hypophosphatemic rickets as a result of a loss of function mutation in the NPP1 gene." (PMID 22359666, 2012). "The phenotypic profiles of the Fam20c-deficient mice resemble those of hereditary hypophosphatemic rickets in humans and rodents resulting from mutations in molecules affecting the regulation of FGF23." (PMID 22615579, 2012). "Non-FGF23 mediated forms of hypophosphatemic rickets include autosomal recessive hereditary hypophosphatemic rickets with hypercalciuria secondary to biallelic variants in the solute carrier family 34-member 3 (SLC34A3) gene encoding the sodium-dependent phosphate transport protein 2C." (PMID 41445557, 2025). "Most cases of hypophosphatemic rickets are associated with increased serum FGF23 levels." (PMID 39482539, 2024). "Although various types of hypophosphatemic rickets are associated with FGF23, the underlying molecular mechanism and various causative factors for excessive FGF23 production remain unclear." (PMID 39482539, 2024).
hypophosphatemic rickets (continued). "Clinical symptoms include craniosynostosis, facial dysmorphism, delayed eruption of teeth and growth impairment, which may be associated with hypophosphatemic rickets due to enhanced bone FGF23-synthesis." (PMID 34910242, 2022). "Fibroblast-growth factor 23 (FGF23)-associated hypophosphatemic rickets was historically treated with frequent doses of oral phosphate salts in combination with active vitamin D, whereas tumor-induced osteomalacia (TIO) should primarily undergo tumor resection, if possible." (PMID 35352187, 2022). "In addition to FGF23, several causative genes for hereditary hypophosphatemic rickets are highly expressed in osteocytes." (PMID 36246908, 2022). "Both TIO and these inherited forms of hypophosphatemic rickets are associated with elevated FGF23." (PMID 35016725, 2022). "Both processes arephysiologically essential: loss-of-function mutations in FAM20C cause increased bloodconcentrations of intact FGF23 and hypophosphatemic rickets, whereas loss-of-function mutationsin GalNT3 result in an FGF23 deficiency-like phenotype in mice and men." (PMID 29096595, 2017). "TM5614 may be a therapeutic candidate for FGF23‐associated hypophosphatemic rickets." (PMID 38050660, 2024). "Moreover, it is a valuable diagnostic tool in primary disorders associated with FGF23 overproduction, such as hypophosphatemic rickets or tumor-induced osteomalacia, where it also serves as a therapeutic target following the development of an anti-FGF23 antibody (Burosumab)." (PMID 38634076, 2024). "The global or specific knockout of FAM20C in mineralized tissues in mice can result in hypophosphatemic rickets, along with elevation of fibroblast growth factor 23 and down-regulation of osteoblast differentiation markers." (PMID 39790934, 2025). "It is suggested that the FAM20C- fibroblast growth factor 23-phosphate pathway and osteoblast differentiation disorder play important roles in the occurrence and development of hypophosphatemic rickets." (PMID 39790934, 2025). "Two infants with biliary atresia presented with FGF23-related hypophosphatemic rickets, which improved after liver transplantation due to end-stage liver disease." (PMID 39963340, 2025). "This protein is involved in calcification in bone, and when DMP1 is suppressed, fibroblast growth factor 23 (FGF23) is highly expressed in bone cells; FGF23 in the blood can increase, causing autosomal recessive hypophosphatemic rickets." (PMID 41040543, 2025). "Hypophosphatemic conditions which are FGF23-independent also exist (e.g., hereditary hypophosphatemic rickets with hypercalciuria, nephrolithiasis)." (PMID 39377903, 2025). "CSHS is characterized by epidermal or melanocytic nevi, hypophosphatemic rickets, and high serum levels of the phosphatonin FGF23." (PMID 40291321, 2025). "FGF23 concentrations are increased in FGF23-dependent hypophosphatemic rickets; therefore, these conditions can be distinguished from FGF23-independent hypophosphatemic disorders by measuring the FGF23 concentration." (PMID 38706696, 2024). "The reduced TmP/GFR ratio found in patients with hypophosphatemic rickets is due to an overproduction or reduced degradation of fibroblast growth factor 23 (FGF23)." (PMID 38706696, 2024). "Cutaneous-skeletal hypophosphatemia syndrome (CSHS) is a rare disorder characterized by the presence of melanocytic nevi, dysplastic cortical bony lesions, and fibroblast growth factor 23 (FGF23)-mediated hypophosphatemic rickets." (PMID 39416269, 2024). "Nevertheless, the approval of drugs like burosumab for the treatment of hypophosphatemic rickets signifies a significant advancement in leveraging FGF23 modulation for therapeutic purposes, offering hope for patients afflicted with related disorders." (PMID 38732094, 2024). "High FGF23 concentrations are evident in both hereditary and acquired forms of hypophosphatemic rickets such as TIO." (PMID 38706696, 2024).
hypophosphatemic rickets (continued). "The identification of FGF23 in familial hypophosphatemic rickets has been a step forward in our understanding of mineral homeostasis." (PMID 38634076, 2024). "VDDR is further subclassified into four different forms including VDDR1A, VDDR1B, VDDR2A, and VDDR2B, whereas hypophosphatemic rickets consists of 15 distinct disorders which are grouped into FGF-23-dependent and FGF-23-independent hypophosphatemic rickets." (PMID 36692815, 2023). "Pathogenic variants in the PHEX gene cause rare and severe X-linked dominant hypophosphataemia (XLH), a form of heritable hypophosphatemic rickets (HR) characterized by renal phosphate wasting and elevated fibroblast growth factor 23 (FGF23) levels." (PMID 37568915, 2023). "The use of burosumab in other types of FGF23-related hypophosphatemic rickets, such as TIO, has been proposed and is currently under investigation." (PMID 35381903, 2022). "In a few families, hereditary hypophosphatemic rickets has had an autosomal dominant inheritance pattern (ADHR; MIM 193100) due to a mutation in the gene encoding the Fibroblast Growth Factor 23 gene (FGF23)." (PMID 36011266, 2022). "Patients with HHRH can be distinguished from those with other forms of hypophosphatemic rickets by their high 1,25 vitamin D levels in conjunction with low to normal parathyroid hormone and fibroblast growth factor 23 (FGF23) levels." (PMID 37908277, 2022). "An anti-FGF23 monoclonal antibody, burosumab, has recently been shown to be safe and effective in controlling signs and symptoms in pediatric and adult patients with hypophosphatemic rickets due to FGF-23 excess." (PMID 35381903, 2022). "It was reported that CRISPR/Cas9-mediated ablation of DMP1 in rabbit caused the phenotype similar to human ARHR1, including the elevated serum FGF23 and hypophosphatemic rickets." (PMID 36246908, 2022). "In contrast, plasma FGF23 levels are low in hypophosphatemic patients with hereditary hypophosphatemic rickets with hypercalciuria." (PMID 33660084, 2021). "Affected patients have segmental epidermal nevi, dysplastic cortical bony lesions, and fibroblast growth factor-23 (FGF23)-mediated hypophosphatemic rickets." (PMID 34660853, 2021). "Generally, impaired function of Na-P cotransporter results in P wasting and hypophosphatemic rickets, short stature, bowing, normal or reduced FGF23 levels, hypercalciuria, elevated 1,25(OH)2D3 and low PTH levels." (PMID 34068220, 2021). "Mice with Fam20C deletion exhibit an increase in bioactive serum FGF23 leading to the development of hypophosphatemic rickets and skeletal defects, which can be partially reversed by feeding the mice a high-phosphate-containing diet." (PMID 33759783, 2021). "In patients with hereditary hypophosphatemic rickets with hypercalciuria, low plasma FGF23 leads to high serum 1,25(OH)2D levels." (PMID 33660084, 2021). "For instance, high levels of FGF23 are present in some forms of rare disorders known as hypophosphatemic rickets (HR), which have different etiopathogenesis, including genetic diseases, and share a similar phenotype caused by excessive renal phosphate loss." (PMID 34208131, 2021). "Intriguingly, proteolysis-resistant missense alterations adjacent to Ser180 (R176Q, R179W, and R179Q) activate FGF23 leading to hypophosphatemic rickets." (PMID 33759783, 2021). "These panels include several genes (DMP1, ENPP1, FGF23, PHEX, SLC34A1, FAM20C), which cause hypophosphatemic rickets." (PMID 33660084, 2021). "It was first proposed that osteocytes are endocrine cells in 2006, and the first secreted factor identified was fibroblast growth factor 23 (FGF23), which is highly elevated in osteocytes of patients with hypophosphatemic rickets." (PMID 34650980, 2021). "Differential diagnosis of high serum FGF23 levels include fibrous dysplasia, autosomal dominant or recessive hypophosphatemic rickets and Raine syndrome." (PMID 31993875, 2020).
hypophosphatemic rickets (continued). "A combination of oral phosphorous supplementation and active vitamin D analogs is the conventional therapy to counteract the consequences of excessive FGF23 in hypophosphatemic rickets." (PMID 32733380, 2020). "PHEX indirectly regulates FGF23, and PHEX gene mutation causes hypophosphatemic rickets, a rare hereditary bone disease." (PMID 32733380, 2020). "For example, inactivating mutations in the phosphate-regulating endopeptidase homolog, X-linked (PHEX) gene lead to the upregulation of FGF23 production in patients with XLH, which is the most prevalent form of genetic FGF23-related hypophosphatemic rickets." (PMID 30627598, 2019). "Advancements in pharmacological tools to block FGF-23 have been made, including blocking antibodies, which show efficacy and safety in treating hypophosphatemic rickets in hereditary disorders of FGF-23 excess." (PMID 29946298, 2018). "The non-FGF23-mediated hypophosphatemic rickets includes hypophosphatemic rickets with hypercalciuria, and renal Fanconi syndrome." (PMID 24386581, 2013). "Mutations in four genes, FGF23 itself, PHEX, DMP1 and ENPP1, have been reported to remarkably increase the plasma levels of FGF23, leading to hereditary hypophosphatemic rickets." (PMID 22615579, 2012). "In this study, we used three different FGF23 concentrations (1, 10, and 100 ng/mL), which were not only in line with those used by other groups but also reflected FGF23 levels measured in the serum of patients with hypophosphatemic rickets or other diseases characterized by high FGF23 levels." (PMID 40926139, 2025). "Based on the pathogenesis, XLH is a disorder of FGF23-related hypophosphatemic rickets." (PMID 39415983, 2024). "By contrast, PTH levels are usually in the normal range in patients with phosphopenic rickets, but can be slightly elevated in patients with FGF23-driven phosphopenic rickets, as FGF23 suppresses 1,25(OH)2D levels, which in turn stimulates PTH secretion in the parathyroid glands." (PMID 34910242, 2022). "Furthermore, mice with the transgenic overexpression of high-molecular-weight isoforms of FGF2 in osteoblast lineage cells exhibited elevated FGF23 levels and hypophosphatemic rickets." (PMID 35909535, 2022). "Patients with mild RNS may survive and manifest hypophosphatemic rickets due to elevated FGF23 levels as well as dental anomalies." (PMID 35909535, 2022). "Cutaneous-skeletal hypophosphatemia syndrome (CSHS) constitutes a specific sub-entity in which elevated levels of fibroblast growth factor-23 cause hypophosphatemic rickets that are, to date, not amenable to causal therapy." (PMID 35600592, 2022). "This form of hypophosphatemic rickets is mediated by FGF23 (OMIM #605,380), a hormone that increases renal losses of phosphate, but the etiology of FGF23 increase remains unknown as of yet." (PMID 36461014, 2022). "Children manifesting with hypophosphatemic rickets after early childhood, associated with elevated FGF23 levels, negative family history, and/or negative genetic tests for hereditary causes should be candidates for a TIO diagnostic workup." (PMID 34910242, 2022). "Osteocytes express FGF23 and other multiple genes responsible for hereditary hypophosphatemic rickets, which include phosphate-regulating gene homologous to endopeptidase on X chromosome (PHEX), dentin matrix protein 1 (DMP1), and family with sequence similarity 20, member C (FAM20C)." (PMID 36246908, 2022). "Furthermore, ectopic FGF23 production was identified in a patient with FGF23-related hypophosphatemic rickets with biliary atresia." (PMID 34901334, 2021). "Still, because it is the most common genetic form, single-gene PHEX sequencing may be the appropriate first step in FGF23-mediated hypophosphatemic rickets possibly due to XLH." (PMID 33815294, 2021). "The third pathophysiological category involves FGF23-mediated forms of hypophosphatemic rickets." (PMID 33815294, 2021).
hypophosphatemic rickets (continued). "Besides elevated Klotho levels, patients displayed increased enzymatic activity protein and FGF23 concentrations accompanied by clinical and biochemical findings of hypophosphatemic rickets." (PMID 34068220, 2021). "FGF-23 is mainly secreted by osteocytes and osteoblasts and is upregulated in the circulation in cases of bone disorders characterized by softening and weakening of bones (low bone mineral density) including all types of hypophosphatemic rickets." (PMID 33101055, 2020). "However, expression of both NPT1 and NPT2 was significantly decreased in the Hyp mouse (a mouse model of hypophosphatemic rickets with increased serum FGF23 concentrations), and NPT1 expression is upregulated in Npt2-/- mouse models." (PMID 33027890, 2020). "Non-FGF23-mediated hypophosphatemic rickets may have better response to medical therapy as compared to FGF23-mediated hypophosphatemic rickets in which bone deformity continues to progress on medical therapy and surgical correction is often required." (PMID 24386581, 2013). "The main sources of FGF23 are the osteoblasts and osteocytes in the skeleton, and a number of studies have shown that inactivating mutations in certain molecules expressed by these bone cells increase the plasma level of FGF23, which leads to hereditary hypophosphatemic rickets." (PMID 22615579, 2012). "Indeed, in patients with genetic hypophosphatemic rickets due to high circulating serum FGF23 levels, neither 1,25(OH)2D3 nor urine calcium is elevated; namely, high levels of FGF23 per se do not cause hypercalciuria." (PMID 29457024, 2017). "In the last decades FGF23 has proven its worth in the diagnosis of TIO and hypophosphatemic rickets." (PMID 35665817, 2023). "The studies on the pathogenesis of hypophosphatemic rickets made it possible to distinguish FGF-23-dependent and non-FGF-23-dependent hypophosphatemic rickets." (PMID 35956239, 2022). "High serum FGF23 levels in conjunction with elevated levels of PTH contribute to the pathogenesis of renal phosphate wasting and hypophosphatemic rickets." (PMID 32271147, 2020). "Burosumab (KRN23) is a neutralizing antibody to FGF23 that has emerged as a promising treatment for XLH and hypophosphatemic rickets." (PMID 32547492, 2020). "Excess of FGF23 induces hypophosphatemic diseases and among these XLH is the most prevalent form of genetic FGF23-related hypophosphatemic rickets (~ 80% of all cases of hypophosphatemic rickets)." (PMID 40926139, 2025). "Forms of hypophosphatemic rickets independent of FGF23 due to genetic defects of renal tubular phosphate reabsorption are treated with oral phosphate only, since they are associated with excessive 1,25-dihydroxyvitamin D production." (PMID 35352187, 2022). "Anti-FGF23 antibody or gene therapy targeting DMP1, FGF23, or PHEX, could be a future direction to treat hypophosphatemic rickets." (PMID 32733380, 2020). "The treatment of hypophosphatemic rickets is done by the oral administration of phosphorus and vitamin D. Currently, growth hormone and KRN23 a recombinant human monoclonal antibody targeting FGF23 are under investigation for hypophosphatemic rickets." (PMID 27340574, 2016). "Mutations in the kidney sodium phosphate channel as occurring in hereditary hypophosphatemic rickets with hypercalciuria can result in phosphate wasting independent of FGF23." (PMID 22934198, 2012). "In contrast, enthesopathy is not described in FGF23-independent forms of hypophosphatemic rickets, such as hereditary hypophosphatemic rickets with hypercalciuria due to pathogenic variants in SLC34A3, which encodes the renal tubular NPT2 phosphate transporter." (PMID 37871131, 2024). "Consequently, genetic disorders caused by inactivating GalnT3 and Fam20C mutations, such as familial tumoral calcinosis and hypophosphatemic rickets, are unlikely to be influenced by VDR-mediated regulation of FGF23 cleavage." (PMID 37681408, 2023).